ETV4 (ETS variant transcription factor 4)
Diseases named in the same sentence as ETV4 in open-access papers (continued):
Sharing a sentence is not in itself a finding about the gene and the disease.
prostate carcinoma (61 papers, 2008 to 2025). A carcinoma that arises from epithelial cells of the prostate gland. "Further investigations are needed to completely define the role, if any, of the alternative ETV4 variants in defining the features and the development trajectories of prostate cancer." (PMID 37002241, 2023). "As half of the genes included in the six cancer-specific pathways were related to the metabolism pathway, interestingly, the metabolic pathway was highly associated with the ETV4 subtype of prostate cancer." (PMID 36289913, 2022). "Genes associated with ETV4-fusion-positive prostate cancers were used as the input, and four therapeutic candidate targets, PARP1, NQO1, HSPA5, and TOP1, and the respective selective drugs, olaparib, amrubicin, fluorouracil, and irinotecan, were identified." (PMID 36289913, 2022). "PEA3 transcription factors Etv1, Etv4, and Etv5 overexpression is associated with the development and metastasis of prostate cancer, colorectal cancer, and ovarian cancer." (PMID 30610188, 2019). "In particular, these genes have been found to be associated with various types of cancer, such as prostate cancer, where ETV1 and ETV4 were often found overexpressed." (PMID 41304759, 2025). "Members of the PEA3 (ETV5, ETV4 and ETV1) and ERG (FEV, FLI1 and ERG) sub‐families can behave as oncogenes, with evidence of oncogenic expression in ERG and PEA3 genes occurring early on in prostate cancer development." (PMID 39410867, 2024). "CANT1 encodes the androgen-regulated protein CANT1, which has previously been found to form a fusion transcript with ETV4 in prostate cancer." (PMID 39010058, 2024). "In this study, cellular signaling pathway analysis was extensively performed, and novel therapeutic targets and candidate drugs for ETV4-fusion-positive prostate cancer patients were systematically identified." (PMID 36289913, 2022). "We further performed gene–drug network analysis and investigated therapeutic targets and candidate drugs in ETV4-fusion-positive prostate cancer." (PMID 36289913, 2022). "A total of 85 genes were significantly highly expressed, and only PXN was downregulated in ETV4-fusion-positive prostate cancer." (PMID 36289913, 2022). "CDK19 was the cancer-related gene most highly correlated with ETV4 expression, confirming its oncogenic function in ETV4-fusion-positive prostate cancer." (PMID 36289913, 2022). "We previously reported that ERG subtypes of prostate cancer have altered androgen receptor signaling, similar to the ETV4 subtypes of prostate cancer shown in the current study." (PMID 36289913, 2022). "To examine key cellular signaling pathways and explore therapeutic targets and drugs for ETV4-fusion-positive prostate cancer, we analyzed RNA sequencing data and clinical information for prostate cancer." (PMID 36289913, 2022). "PARP1, NQO1, HSPA5, and TOP1 were identified as potential molecular targets for ETV4-fusion-positive prostate cancer, and olaparib, amrubicin, fluorouracil, and irinotecan were suggested as candidate drugs, respectively." (PMID 36289913, 2022). "ETV4 (ETS Translocation Variant 4) is one of an ETS family transcription factor and is aberrantly expressed in a variety of human tumors such as prostate cancer and non-small cell lung cancer." (PMID 35280808, 2022). "Considering that ETV4 rearrangement is mutually exclusive with other oncogenic driver mutations in prostate cancer, the study of the molecular features, specific therapeutic targets, and potential drugs for ETV4 subtypes of prostate cancer are needed." (PMID 36289913, 2022). "The best known fusion genes associated with prostate cancer involve ETS transcription factor family members and the androgen-regulated promotor TMPRSS2 (TMPRSS2:ERG, TMPRSS2:ETV1, and TMPRSS2:ETV4)." (PMID 35625354, 2022). "Cellular signaling pathway analysis was performed using the selected 393 genes via ORA to investigate altered signaling pathways in the ETV4-fusion-positive prostate cancer group." (PMID 36289913, 2022).
prostate carcinoma (continued). "Here, we have identified significantly altered genes and oncogenic signaling pathways in ETV4-fusion-positive prostate cancer, and we suggest therapeutic targets and potential drugs for ETV4-fusion-positive prostate patients." (PMID 36289913, 2022). "The structural variation of ETS variant transcription factor 4 (ETV4), defined as another driver mutation, was observed in 2% of prostate cancers." (PMID 36289913, 2022). "Next, we performed gene–drug network analysis and identified new therapeutic targets and drugs for ETV4-fusion-positive prostate cancer." (PMID 36289913, 2022). "Taken together, we have provided information on altered cellular signaling pathways and therapeutic targets for ETV4-fusion-positive prostate cancer." (PMID 36289913, 2022). "In the study, 774 genes were altered by either overexpressing or knocking-down ETV4 in a prostate cancer cell line, and signaling pathways were analyzed using these genes." (PMID 36289913, 2022). "A large clinical study should be warranted for evaluation of the effects of olaparib on the ETV4 subtype of prostate cancer in the future." (PMID 36289913, 2022). "ETV4-fusion-positive prostate cancers were selected based on structural variation data and gene expression data according to a previous report." (PMID 36289913, 2022). "In a mouse model, ETV4 promotes prostate cancer metastasis in response to coactivation of PI3-kinase and Ras signaling pathways." (PMID 33858332, 2021). "MMPs, such as MMP13 and urokinase plasminogen activator (uPA) are also transcriptionally regulated by ETV4, which are involved in the ETV4-driven malignant phenotypes in prostate cancer and breast cancer." (PMID 32018225, 2020). "ETV4 overexpression in the prostate is observed in only a relatively small subset of prostate cancer patients (about 1–5%); however, since prostate cancer is common, these results are potentially relevant for a significant number of patients." (PMID 32791988, 2020). "Based on genomic profiles, prostate cancer can be divided into seven molecular subtypes which bear distinct oncogenic drivers including fusions with ETS family members (ERG, ETV1, ETV4, and FLI1) and mutations in SPOP, FOXA1, and IDH1." (PMID 33273988, 2020). "ETV4 is one of the ETS proteins overexpressed in prostate cancer (PC) as a result of recurrent chromosomal translocations." (PMID 32791988, 2020). "Lastly, ETV4 and ETV5 are highly homologous to ETV1 and also implicated in prostate cancer development." (PMID 31160676, 2019). "ETV-4 has been reported to be associated with ETS-2 and ERG, and formed a complex integrated transcriptional network in PC3 cell nuclear extracts and prostate cancer tissues." (PMID 29915163, 2018). "A recent study selected the DU-145 prostate cancer cell line as a model to address the oncogenic role of ETV4 in prostate cells." (PMID 25595908, 2015). "The fusion of the TMPRSS2 gene with E-twenty six (ETS) family genes like ETV1, ERG and ETV4 occurs in up to 70% of all prostate cancers and is therefore a specific biomarker for prostate cancer diagnostics." (PMID 23341502, 2013). "The study leaves the question of whether ETV4 expression is elevated in prostate cancer tissues uncertain, necessitating further research." (PMID 40469297, 2025). "ETV4 was found medium-high expression in prostate cancer, breast cancer, non-small cell lung cancer and digestive tract cancer, including oral cancer, esophageal cancer, gastric and colorectal cancer, and was negatively correlated with patient prognosis and survival." (PMID 41281746, 2025). "Reasoning that the dosage of ETS protein is crucial in ETS-drive prostate cancer tumorigenesis, we created a low dosage (ETV4WT) level and a high dosage (ETV4AAA) level of ETV4 protein through increased ETV4 protein stability by mutating the conserved ExxVPD motifs responsible for COP1 degradation." (PMID 37018402, 2023). "In prostate cancer, ETV4 is one of the ETS genes involved in chromosomal translocations." (PMID 37002241, 2023).
prostate carcinoma (continued). "A previous study showed that anti-androgen therapy has a better effect on tumorigenesis in the ERG subtypes of prostate cancer, and we expect a similar effectiveness from anti-androgen therapy in ETV4-fusion-positive prostate cancer, based on its unique features of cellular signaling pathways." (PMID 36289913, 2022). "In this study, we discovered that six cancer-specific cellular signaling pathways, the irinotecan pathway, metabolism, androgen receptor signaling, interferon signaling, MAPK/NF-kB signaling, and the tamoxifen pathway, were altered in the ETV4 subtype of prostate cancer." (PMID 36289913, 2022). "MAPK/NF-kB signaling was also altered in the ETV4 subtype of prostate cancer." (PMID 36289913, 2022). "Of these, 19 genes had previously reported oncogenic functions in prostate cancer, which suggests that these genes could specifically function in ETV4-fusion-positive prostate cancers." (PMID 36289913, 2022). "Thus, we here systematically analyzed RNA sequencing (RNA-seq) data obtained from The Cancer Genome Atlas (TCGA) database and identified oncogenic signaling pathways activated in ETV4-fusion-positive prostate cancer, which results in ETV4 overexpression." (PMID 36289913, 2022). "ETV4 overexpression was observed in various cancer types, such as prostate cancer, bladder cancer, gastric cancer, colon cancer, and hepatocellular carcinoma, and the underlying mechanism and oncogenic function have been revealed, which suggest the importance of ETV4 in cancer research." (PMID 36289913, 2022). "However, the molecular features of ETV4 fusion in prostate cancer are not fully understood, and drugs targeting ETV4 fusion have not been developed." (PMID 36289913, 2022). "For example, PXN, which is known as an oncogene in prostate cancer, has higher expression in the ERG and SPOP subtypes of prostate cancer, as compared to normal cells, and lower expression in ETV1 and ETV4 subtypes of prostate cancer, as compared to normal cells." (PMID 36289913, 2022). "ETV4 increases metastasis by activating PI3K kinase-RAS signaling in mouse prostate cancer models." (PMID 36289913, 2022). "ETV4 rearrangement has lately been discovered as a driver gene in 2% of prostate cancers." (PMID 36289913, 2022). "Previous studies have shown the effects of ETV4 silencing in the reduction of cell proliferation, migration and invasion, in both colon and prostate cancer cell lines, but no data on colony formation has been previously associated with ETV4 in CRCs." (PMID 33648461, 2021). "ETV4 is overexpressed in several cancers and in a relatively small fraction of prostate cancers." (PMID 32791988, 2020). "This multi-faceted role of ETV4 in prostate cancer makes it a potential target for novel therapeutic approaches that could be explored in this ETV4 transgenic model." (PMID 32791988, 2020). "In an analysis of 333 individual prostate cancer exomes, TCGA identified seven subtypes defined either by gene fusions involving the ETS family (59% of cases), specifically ERG, ETV1, ETV4, or FLI1, or recurrent mutations (15% of cases) in SPOP, FOXA1, or IDH1." (PMID 28423598, 2017). "But although much is known about how PEA3/ETV4 is involved in breast or prostate cancer, very little is understood about how it regulates motor neuron connectivity, retinal development or ganglion cell differentiation, or indeed which promoters are Pea3 targets in the nervous system." (PMID 28158215, 2017). "We also found a fusion between the KLK2 gene and the ETS gene ETV4 in clinical prostate cancer." (PMID 19461893, 2009). "Moreover, PXN expression in ETV4-fusion-positive prostate cancer was lower compared to normal." (PMID 36289913, 2022). "Indeed, therapeutic targets and candidate targeted drugs for ETV4-overexpressing prostate cancer remain unknown." (PMID 36289913, 2022).
prostate carcinoma (continued). "Using a panel of prostate cancer cell lines we found co-overexpression of ETV1 and ETV4 in two cell line models of advanced prostate cancer (MDA-PCa-2b and PC3) and questioned whether these PEA3 family members would cooperate in the acquisition of oncogenic properties or show functional redundancy." (PMID 25595908, 2015). "Only two publications have shown a role for ETV4 in EMT via ZEB1 regulation in breast and prostate cancers." (PMID 40275610, 2025). "ETV4, one of ETS proteins overexpressed in prostate cancer, promotes migration, invasion, and proliferation in prostate cells." (PMID 37002241, 2023). "Fortunately, cancer driver genes in prostate cancer, ERG, ETV1, ETV4, SPOP, and FOXA1, have been identified and their roles have been proved through basic and clinical research." (PMID 36579559, 2022). "In addition, our study suggests that olaparib could also be actionable in the ETV4 subtype of prostate cancer, regardless of BRCA mutation." (PMID 36289913, 2022). "PXN expression was relatively high in ERG1- and FLI1-fusion-positive prostate cancers and SPOP-mutant prostate cancer, but it was relatively low in ETV1- and ETV4-fusion-positive prostate cancers." (PMID 36289913, 2022). "More recently, co-expression of ETV1 and ETV4 was found in PC-3 and MDA-PCa-2b prostate cancer cell lines, representing models of advanced disease." (PMID 33634124, 2021). "In the fusion transcript TMPRSS2-ETV4, found in prostate cancer patients, a sequence upstream of the TMPRSS2 gene is juxtaposed to the last 9 bp of intron 2 of ETV4 gene." (PMID 32791988, 2020). "Whilst this manuscript was under review, it has been reported that indeed ETV1, ETV4 and ETV5 can transcriptionally upregulate TAZ in prostate cancer cells." (PMID 30952872, 2019). "In prostate cancer, three members of the ETS family (ERG, ETV1, and ETV4) are commonly overexpressed due to chromosomal translocations." (PMID 30603056, 2018). "For example, ETV4 directly regulates MYC and other proliferation genes in prostate cancer cell lines." (PMID 29371979, 2017). "The discovery and functional validation of recurrent gene fusions of 5 Ets factor genes (ETV1, ETV4, ETV5, ERG, Fli1) in prostate cancer highlights the relevance of Ets transcription factors as oncogenes in prostate cancer." (PMID 26885618, 2016). "The most prevalent gene fusion is the TMPRSS2-ERG, present in nearly half of all human prostate cancers, followed by rearrangements involving the ETV1, ETV4, ETV5 and FLI1 genes, often with promoter fusion partners other than TMPRSS2." (PMID 25595908, 2015). "Conversely, some lineage-specific genes are seen to serve as 5′ partners across multiple different 3′ genes; for example, TMPRSS2 and SLC45A3 in prostate cancer have been observed as 5′ partners of ERG, ETV1, ETV4, ETV5, BRAF, and ELK4." (PMID 26684754, 2015). "ETS family gene fusions, primarily including ERG (and less frequently, ETV1, ETV4, ETV5 or FLI1), are found in approximately 50 % of prostate cancers, the most common fusion being TMPRSS2-ERG." (PMID 26684754, 2015). "Recurrent gene fusions involving several members of ETS transcription factor family (ERG, ETV1, ETV4 or ETV5) were found to be the most frequent genetic alterations in prostate cancer, which can be detected in as many as 50%–70% of prostate cancer samples." (PMID 23852643, 2013). "Especially TMPRSS2 fuses with ERG and Ets family genes such as ETV1, ETV4 and ETV5 in prostate cancers." (PMID 21347291, 2011). "We included oligonucleotide probe sets for the three major members of the ets family involved in prostate cancer: ERG, ETV1, and ETV4, as well as their translocation partner TMPRSS2." (PMID 18846227, 2008). "It is possible that like the fusions between TMPRSS2 and ERG, ETV1, ETV4 and ETV5, other functionally identical fusions are involved in changes in gene expression and prostate cancer development but are yet to be discovered." (PMID 18694509, 2008).
prostate carcinoma (continued). "Our panel(s) included probe sets for three members of the ets family involved in prostate cancer; ERG, ETV1, and ETV4, as well as their translocation partner, TMPRSS2." (PMID 18846227, 2008). "A previous study found that ETV4 knockdown in metastatic murine prostate cancer cells abrogates the metastatic phenotype but does not affect tumor size." (PMID 39484215, 2024). "The mRNA expression of ETV4 was higher in ETV4-fusion-positive prostate cancer, as compared to that in ETV4-fusion-negative prostate cancer." (PMID 36289913, 2022). "Patient characteristics between 14 ETV4-fusion-positive prostate cancers and 86 ETV4-fusion-negative prostate cancers were analyzed." (PMID 36289913, 2022). "Considering the absence of targeted drugs for the ETV4 subtype of prostate cancer, our study will allow a step forward in investigations of treatments." (PMID 36289913, 2022). "Additionally, TMPRSS2-ERG fusions exist in approximately 50% of prostate cancer cases, with TMPRSS2-FEV, -ETV1, -ETV4, and -ETV5 fusions found in other patients." (PMID 34145397, 2021). "ETV1, ETV4, and ETV5, which belong to the PEA3 group of genes, are types of ETS transcription factors that are known to promote several types of cancer such as Ewing-like sarcoma, gastric cancer, colorectal cancer, hepatocellular carcinoma and prostate cancer." (PMID 34830169, 2021). "The role of ERG and ETV1 in prostate cancer has been thoroughly studied, whereas the mechanisms whereby overexpression of ETV4 mediates oncogenesis in the prostate have not been investigated in depth." (PMID 32791988, 2020). "About 50–70% of prostate carcinomas harbor common chromosomal rearrangements fusing one of the ETS transcription family genes (ERG, ETV1, ETV4 or FLI1) with androgen-regulated genes, most commonly TMPRSS2, leading to disruption of androgen receptor signaling via activation of EZH253." (PMID 32873863, 2020). "Overall, clinical evidence and in vitro studies strongly suggest that ETV4 plays a key role in prostate cancer in a non-negligible proportion of patients." (PMID 32791988, 2020). "Some of these genes were already extensively studied in prostate cancer, mostly those upregulated in tumor tissue: SPINK1 (Top17, logFC 4.8), ETV4 (Top63, logFC 3.6), PCA3 (Top79, logFC 3.5), TDRD1 (Top86, logFC 3.4), AMACR (Top105, logFC 3.2), DLX1 (Top110, logFC 3.1), HOXC6 (Top268, logFC 2.3)." (PMID 31170942, 2019). "In prostate cancer, many genes from the ETS family participate in fusion transcripts with transmembrane serine protease isoform 2 (TMPRSS2); in fact, three ETS members (ERG, ETV1, and ETV4) contribute to about 80% of TMPRSS2 fusion." (PMID 29455655, 2018). "Using the TaqMan Low Density Array (TLDA) technology, we evaluated the expression of the five ETS genes known to be involved in genomic rearrangements in PCa (ERG, ETV1, ETV4, ETV5 and FLI1) in a panel of cell lines representing various subtypes of prostate cancer." (PMID 25595908, 2015). "Using the expression data of our series of prostate carcinomas subtyped for ETS rearrangements, we show that both PC3 and MDA-PCa-2b cells have co-overexpression of ETV1 and ETV4, both ETS in higher levels than those of ERG in VCaP cells, the in vitro model of the TMPRSS2-ERG rearrangement." (PMID 25595908, 2015). "Gene fusions found in prostate cancer often involve the ERG, ETV1, or ETV4 gene." (PMID 21789226, 2011). "The protein dosage of PEA3 subfamily of ETS transcription factors ETV1, ETV4, and ETV5 is regulated through both transcription and ubiquitylation-mediated protein degradation by E3 ubiquitin ligase COP1, a tumor suppressor in both human prostate cancer and in GEM models of prostate cancer." (PMID 37018402, 2023).